SLC13A1 (solute carrier family 13 member 1)
Description:
Sodium:sulfate symporter that mediates sulfate reabsorption in the kidney and small intestine. Can also mediate the transport of selenate and thiosulfate (By similarity).
Synonyms: NAS1; NaSi-1
Tractability: Small molecule: a structure with a bound ligand is known. Antibody: its Gene Ontology location is reachable by antibodies, with high confidence; UniProt places it where antibodies can reach, with medium confidence; UniProt predicts a signal peptide or a membrane-spanning region.
Gene: Protein-coding gene on chromosome 7 (123,113,531 to 123,200,047, reverse strand). Ensembl gene ENSG00000081800.
Subcellular location: Apical cell membrane
Pathways (Reactome):
Transport of small molecules: Sodium-coupled sulphate, di- and tri-carboxylate transporters
Gene Ontology:
Molecular function: sodium:sulfate symporter activity; monoatomic anion:sodium symporter activity; secondary active sulfate transmembrane transporter activity; solute:sodium symporter activity; transmembrane transporter activity
Biological process: sodium ion transport; sulfate transmembrane transport; transmembrane transport; monoatomic anion transmembrane transport; sodium ion transmembrane transport
Cellular component: apical plasma membrane; plasma membrane; membrane
Genetic constraint (gnomAD): Loss-of-function variants: 47 observed, 57.22 expected, observed/expected ratio (o/e) 0.82, 90% interval 0.65 to 1.05. The upper end of that interval is the gene's LOEUF score, 1.05, which puts it in group 4 of 6, group 1 being the genes least tolerant of losing a copy. Missense variants: 644 observed, 669.98 expected, observed/expected ratio (o/e) 0.96, 90% interval 0.9 to 1.03. Synonymous variants: 247 observed, 235.13 expected, observed/expected ratio (o/e) 1.05, 90% interval 0.95 to 1.17.
Homologues: Orthologues: chimpanzee SLC13A1 (99% identical), macaque SLC13A1 (91% identical), pig SLC13A1 (88% identical), dog SLC13A1 (87% identical), rabbit SLC13A1 (84% identical), rat Slc13a1 (83% identical), mouse Slc13a1 (81% identical), guinea pig SLC13A1 (77% identical), tropical clawed frog slc13a1 (69% identical), zebrafish slc13a1 (54% identical), Caenorhabditis elegans nac-1 (33% identical), Caenorhabditis elegans B0285.6 (31% identical), and 6 more. Paralogues in human: SLC13A4 (50% identical), SLC13A2 (45% identical), SLC13A5 (41% identical), SLC13A3 (40% identical), OCA2 (16% identical).
Diseases named in the same sentence as SLC13A1 in open-access papers:
SLC13A1 is named in the same sentence as 23 diseases in open-access papers, as found by Europe PMC text mining. Sharing a sentence is not in itself a finding about the gene and the disease. The quoted sentences say what the papers report.
hypersulfaturia (3 papers, 2012 to 2025). "Deletion of SLC13A1 would be expected to cause decreased serum levels (hyposulfatemia) and increased urinary excretion (hypersulfaturia) of sulfate." (PMID 23300579, 2012). "Additionally, loss-of-function mutations in human SLC13A1 gene that cause hypersulfaturia and hyposulfatemia have also been identified." (PMID 40557318, 2025). "Loss of murine SLC13A1 has been shown to result in hyposulfatemia and hypersulfaturia." (PMID 23300579, 2012). "Further experiments are needed to demonstrate that deletion of SLC13A1 causes hypersulfaturia." (PMID 23300579, 2012). "Previous studies have shown that targeted disruption of Slc13a1 leads to hypersulfaturia, hyposulfatemia and reduced sulfonation capacity in mice." (PMID 40557318, 2025). "We tested for hyposulfatemia and hypersulfaturia in affected Miniature Poodles by measuring circulating and excreted levels of sulfate in samples obtained from each SLC13A1 genotypic class." (PMID 23300579, 2012). "The SLC13A1 knockout mouse models show notable hyposulfatemia and hypersulfaturia, suggesting the essential role of NaS1 in maintaining sulfate homeostasis of which perturbations could influence a wide range of physiological processes including metabolism, growth, behavior, and fecundity." (PMID 38552027, 2024).
intervertebral disc disorder (3 papers, 2022 to 2025). "A genome-wide association study of intervertebral disc disorder performed by Bjornsdottir et al38 in 2022 found SLC13A1 nonsense variants p.(Arg12∗) and p.(Trp48∗) conferred the largest risk effect (LOF burden OR = 1.44, P = 3.1 × 10−11)." (PMID 39925707, 2025). "Recently, rare loss-of-function variants of SLC13A1 have been demonstrated to be associated with hyposulfatemia, back pain, and intervertebral disc disorder, another example of painful cartilage disease." (PMID 36719378, 2023).
Obesity (3 papers, 2022 to 2025). Accumulation of substantial excess body fat. "The mEC1 population showed an obesity-induced downregulation of transporters of major ions (Slc34a1, Slc4a4, Slc22a8, Slc13a1, Slc22a18 and Slc5a12), neutral amino acids (Slc6a19) and glucose (Slc5a2)." (PMID 36400935, 2022). "Furthermore, obesity led to the up-regulation of sodium transporters (Slc13a1, Slc22a8, Slc17a1, Slc17a3) and the down-regulation of structural proteins (Col4a3, Col4a4) as well as Na/K-ATPase subunits encoded by Atp1a1, Atp1b1, suggesting impaired sodium metabolism and underlying renal injury." (PMID 41133844, 2025). "Inhibitors which target Slc13a1 and agonists which target Nr1i2 or Ago2 are predicted to have a similar BL6-specific protective effect against diet-induced obesity." (PMID 37871105, 2023).
osteochondrodysplasia (3 papers, 2012 to 2025). A term referring to disorders characterized by abnormalities in the development of bones and cartilage. "The essentiality of sulfate for proper bone and cartilage formation is demonstrated by the spectrum of osteochondrodysplasias in humans with homozygous, loss-of-function mutations in SLC26A2, as well as dog and sheep with homozygous loss-of-function mutations in Slc13a1." (PMID 27412988, 2016). "None of the human osteochondrodysplasias have been tied to SLC13A1 mutations, suggesting species-specific background effects that may either suppress or exacerbate SLC13A1 loss-of-function." (PMID 23300579, 2012). "SLC13A1 does not appear to be expressed in cartilage or bone, indicating that the osteochondrodysplasia that results from deletion of SLC13A1 is a metabolic disorder, likely impacting other systems and resulting in phenotypes that have not yet been described clinically." (PMID 23300579, 2012).
Anxiety (1 paper, 2022). Intense feelings of nervousness, tension, or panic often arise in response to interpersonal stresses. "Traits tested were akin to those suggested by reports of SLC13A1 LoF BMD, cholesterol levels, liver parameters, dehydroepiandrosterone levels, epilepsy autism, anxiety and depression." (PMID 35110524, 2022).
chondrodysplasia (1 paper, 2019). "Thus, it appears that mutations in solute carrier families (e.g., in genes SLC4A2 and SLC13A1), can cause bone disorders (e.g., chondrodysplasia) in livestock." (PMID 31600309, 2019). "However, we also found candidate gene SLC13A1 on BTA4, which seems to be associated with bone disorders (such as chondrodysplasia) in Simmental beef cattle." (PMID 31600309, 2019).
infection (2 papers, 2014 to 2020). The state of being infected such as from the introduction of a foreign agent such as serum, vaccine, antigenic substance or organism. "In addition, higher expression of solute carrier family genes (Slc13a1, Slc26a3, Slc2a2, Slc40a1, Slc5a1, and Slc6a19) was seen in the gastric tissue of Muc1−/− mice compared with WT at sham and 8 h infection." (PMID 32793510, 2020).
bone disorder (1 paper, 2019). "Therefore, we speculate that a mutation in gene SLC13A1 may be responsible for bone disorders, especially in Simmental beef cattle." (PMID 31600309, 2019).
musculoskeletal disorders (1 paper, 2025). "We further investigated the association between the same six functional, sulfate-associated QVs in SLC13A1 and SLC26A1 and musculoskeletal disorders, fractures and injuries in the UKB, for which at least two carriers with and without disease were present." (PMID 39747595, 2025).
neurological disorders (1 paper, 2025). "SLC26A1 and SLC13A1 are two sulfate transporters that have been implicated in sulfate homeostasis and neurological disorders." (PMID 40869915, 2025).
tumor (1 paper, 2022). "The dysregulation of SLC13A1 and SLC6A19 are reported to affect various type of tumor progression including ccRCC." (PMID 36090028, 2022).
SLC13A1 also shares sentences with these, for which no sentence is quoted: metabolic disorder (2 papers); autism spectrum disorder (1); calcium oxalate kidney stone (1); cartilage disease (1); depression (1); genetic disorder (1); metabolic syndrome (1); nephrocalcinosis (1); osteoarthritis (1); renal carcinoma (1); scoliosis (1); skeletal dysplasia (1).